BRD8 (bromodomain containing 8)
Description:
May act as a coactivator during transcriptional activation by hormone-activated nuclear receptors (NR). Isoform 2 stimulates transcriptional activation by AR/DHTR, ESR1/NR3A1, RXRA/NR2B1 and THRB/ERBA2. At least isoform 1 and isoform 2 are components of the NuA4 histone acetyltransferase (HAT) complex which is involved in transcriptional activation of select genes principally by acetylation of nucleosomal histones H4 and H2A. This modification may both alter nucleosome - DNA interactions and promote interaction of the modified histones with other proteins which positively regulate transcription. This complex may be required for the activation of transcriptional programs associated with oncogene and proto-oncogene mediated growth induction, tumor suppressor mediated growth arrest and replicative senescence, apoptosis, and DNA repair. NuA4 may also play a direct role in DNA repair when recruited to sites of DNA damage. Component of a SWR1-like complex that specifically mediates the removal of histone H2A.Z/H2AZ1 from the nucleosome.
Synonyms: SMAP; SMAP2; p120
Tractability: PROTAC: UniProt records ubiquitination sites on it; ubiquitination databases record sites on it; its protein half-life has been measured; a small molecule that binds it is known.
Target class: Epigenetic regulator; Bromodomain; Reader
Gene: Protein-coding gene on chromosome 5 (138,139,770 to 138,178,953, reverse strand). Ensembl gene ENSG00000112983.
Subcellular location: Nucleus
Subcellular location (Human Protein Atlas): Nucleoplasm; Mitochondria
Pathways (Reactome):
Chromatin organization: HATs acetylate histones
Gene Ontology:
Molecular function: nuclear thyroid hormone receptor binding; protein binding; transcription coactivator activity
Biological process: cellular response to thyroid hormone stimulus; positive regulation of double-strand break repair via homologous recombination; positive regulation of transcription by RNA polymerase II; regulation of cell cycle; cell surface receptor signaling pathway; positive regulation of DNA-templated transcription; regulation of apoptotic process; regulation of double-strand break repair
Cellular component: NuA4 histone acetyltransferase complex; nucleoplasm; nucleosome; nucleus; Swr1 complex
Genetic constraint (gnomAD): Loss-of-function variants: 61 observed, 138.16 expected, observed/expected ratio (o/e) 0.44, 90% interval 0.36 to 0.55. The upper end of that interval is the gene's LOEUF score, 0.55, which puts it in group 2 of 6, group 1 being the genes least tolerant of losing a copy. Missense variants: 1,081 observed, 1,535.5 expected, observed/expected ratio (o/e) 0.7, 90% interval 0.67 to 0.74. Synonymous variants: 500 observed, 530.67 expected, observed/expected ratio (o/e) 0.94, 90% interval 0.88 to 1.01.
Homologues: Orthologues: chimpanzee BRD8 (99% identical), macaque BRD8 (98% identical), dog BRD8 (92% identical), pig BRD8 (91% identical), rat Brd8 (82% identical), guinea pig BRD8 (67% identical), mouse Brd8 (66% identical), rabbit BRD8 (65% identical), tropical clawed frog brd8 (44% identical), zebrafish brd8a (37% identical), zebrafish brd8b (33% identical), Drosophila melanogaster Brd8 (16% identical), and 1 more.
Diseases named in the same sentence as BRD8 in open-access papers:
BRD8 is named in the same sentence as 15 diseases in open-access papers, as found by Europe PMC text mining. Sharing a sentence is not in itself a finding about the gene and the disease. The quoted sentences say what the papers report.
colorectal cancer (5 papers, 2010 to 2022). A primary or metastatic malignant neoplasm that affects the colon or rectum. "One study reported that BRD8 was involved in cellular survival, as well as sensitivity to spindle poisons and proteasome inhibitor in aggressive colorectal cancers." (PMID 32579175, 2020). "BRD8 was previously shown to be over-expressed in metastatic and highly proliferating colorectal cancer cell lines." (PMID 30237520, 2018). "As RNA interference against BRD8 also suppressed proliferation of colorectal cancer cells, BRD8 may be an important down-stream target of MRGBP." (PMID 20051959, 2010). "MRGBP expression is upregulated in colorectal cancer, and MRGBP plays an essential role in cancer cell proliferation by regulating BRD8." (PMID 35924262, 2022).
glioblastoma (5 papers, 2023 to 2025). The most malignant astrocytic tumor (WHO grade IV).
breast carcinoma (2 papers, 2024). "Accordingly, knockdown of TWIST1 or BRD8 or inhibition of PD-L1 significantly enhances the tumor antigen-specific CD8+ T cells to suppress the growth of breast cancer cells." (PMID 38893094, 2024). "We have shown that TWIST1 interacts with TIP60-Com in a BRD8-dependent manner to activate mesenchymal gene expression in ER- breast cancer or TNBC cells." (PMID 38893094, 2024). "The knockdown of TWIST1 or BRD8 largely diminished PD-L1 expression and enhanced the CD8+ T-cell-mediated inhibition of breast cancer cell growth." (PMID 38893094, 2024). "The knockdown of TWIST1 or BRD8 or the blockade of PD-L1 activity can successfully reverse CD8+ T-cell exhaustion and reinvigorate CD8+ T cells, leading them to inhibit the growth of breast cancer cells." (PMID 38893094, 2024).
bipolar disorder (1 paper, 2023). A disorder of the brain that causes unusual shifts in mood, energy, activity levels and the ability to carry out day-to-day tasks. "4/30 placental genes (TSTA3, BRD8, WDR82, SPG7) that were associated with both schizophrenia and bipolar disorder had opposite signs, so they were predicted to be up-regulated in the placentae of individuals who developed one disorder and down-regulated in the other disorder." (PMID 37188697, 2023).
metastatic colorectal cancer (1 paper, 2020). "Targeting BRD8 would improve therapeutic outcome against aggressive/metastatic colorectal cancers." (PMID 32579175, 2020).
prostate carcinoma (1 paper, 2018). A carcinoma that arises from epithelial cells of the prostate gland. "Contrastingly, BRD8 knockdown induces cell death or growth delay in colorectal and prostate cancer cells, and cells surviving BRD8 knockdown are more sensitive to microtubule-depolymerizing agents." (PMID 30237520, 2018).
sarcoma (1 paper, 2025). A usually aggressive malignant neoplasm of the soft tissue or bone. "BRD8 was previously identified in a NuA4 super complex containing PRC2 proteins in sarcoma, however, we did not detect any PRC2 components in the Co‐IP/MS, suggesting changes in H3K27me3 are indirect." (PMID 39656858, 2025).
cancer (11 papers, 2010 to 2025). A tumor composed of atypical neoplastic, often pleomorphic cells that invade other tissues. "BRD8 appears to be involved in the regulation of cancer cell proliferation and the response to chemotherapeutic compounds, which destabilize the cytoskeleton or impede proteasomal function." (PMID 30237520, 2018). "To investigate a possible function of elevated BRD8 expression in the proliferation of cancer cells, we depleted BRD8 in HCT116 cells." (PMID 30237520, 2018). "Scholars suggested that MRGBP has an important function in proliferation of cancer cells through the regulation of bromodomain containing 8 (BRD8)." (PMID 28969065, 2017). "In the majority of samples on the cancer tissue array, we found upregulation of BRD8 when KDM5A was upregulated and downregulation when KDM5A was downregulated." (PMID 21886846, 2011). "Therefore, BRD8 may have an important function for cell proliferation as a down-stream target of MRGBP in cancer cells." (PMID 20051959, 2010). "In our study, higher mRNA and protein expressions of BRD8 were found in HCC, and mRNA expression of BRD8 was remarkably correlated with cancer stages and tumor grades." (PMID 32927435, 2020). "BRD8, an accessory subunit of human NuA4-HAT complex, may function in embryonic or cancer stem cell reprogramming via the c-MYC pathway." (PMID 32927435, 2020). "BRD8 downregulation significantly impairs cancer cell proliferation of colorectal and hepatocellular tumors, albeit there is no direct evidence of modulating the cancer stem cell-like compartment of the tumor." (PMID 36674511, 2023).
tumor (6 papers, 2018 to 2025). "However, the mechanisms through which BRD8 controls cell proliferation, apoptosis and drug resistance in tumor cells are still poorly understood but an intriguing possibility is that this component of the p400/Tip60 complex may participate in genome maintenance." (PMID 30237520, 2018). "High expressions of BRD8, TRAF3, and KITLG were related to hyperfunction of receptors in tumor or immune cell populations, which could in turn influence the survival of patients." (PMID 33790969, 2021).
BRD8 also shares sentences with these, for which no sentence is quoted: breast tumor (1 paper); Cerebellar hypoplasia (1); colon cancer (1); infection (1); microcephaly (1); schizophrenia (1).